MUC13 (mucin 13, cell surface associated)
Diseases named in the same sentence as MUC13 in open-access papers (continued):
Sharing a sentence is not in itself a finding about the gene and the disease.
gastric cancer (10 papers, 2011 to 2025). A primary or metastatic malignant neoplasm involving the stomach. "Taken together, our study identified distinct mucin-microbiome signatures shaping the tumor microenvironment in gastric cancer, with an intestinal or aberrant MUC13 mucin environment associated with a poor outcome." (PMID 37085819, 2023). "In gastric cancer, elevated MUC13 expression, driven by miR-212-3p and miR-132-3p, facilitated tumor progression." (PMID 39309442, 2024). "According to recent studies, MUC13 is overexpressed in gastric cancer cells and liver cancer cells, making it a promising target for cancer therapeutic intervention." (PMID 37395858, 2023). "High expression of MUC13 is regard as an independent prognostic indicator of early-staged gastric cancer." (PMID 27911274, 2017). "MUC1 and MUC2 are already well known to be overexpressed in gastric cancers, however, MUC13, a transmembrane mucin, might play an as-yet-unknown role in cell signaling and epithelial barrier protection." (PMID 39910169, 2025). "In addition, the combined expression of MUC13 with other metaplasia biomarkers is shown to be a prognostic indicator in several types of gastric cancer." (PMID 23899160, 2013). "Recent studies comparing gastric cancer and normal tissue have identified a number of genetic markers, including diagnostic markers [NF2, INHBA, SFRP4], prognostic markers [CD9, CDH17, PDCD6], and gastric cancer-associated genes [MUC13, CLDN1, Ki67 and CD34]." (PMID 22133303, 2011). "Reducing miR‐132‐3p may promote the spread of gastric cancer by targeting MUC13." (PMID 37395858, 2023).
colorectal cancer (9 papers, 2017 to 2025). A primary or metastatic malignant neoplasm that affects the colon or rectum. "High expression of cytoplasmic MUC13 and NF-κB is associated with progression and metastases of colorectal cancer." (PMID 27911274, 2017). "One study demonstrated that MUC13 is required in colonic cells for activation of NF-κB and found that silencing MUC13 significantly reduced NF-κB activation and subsequently sensitized colorectal cancer cells to death." (PMID 41305005, 2025). "In summary, the analysis established a significant positive correlation between MUC13 and RUNX1 expression levels, associated with poor prognosis in colorectal cancer." (PMID 39309442, 2024). "The findings suggested that RUNX1 modulated malignant properties in colorectal cancer cells, essentially through the transcriptional regulation of MUC13, which in turn affected EMT." (PMID 39309442, 2024). "Overall, the results demonstrated that RUNX1 and MUC13 co-modulation distinctly influenced cellular behaviors related to colorectal cancer progression." (PMID 39309442, 2024). "These insights significantly contribute to our understanding of the novel interactions between RUNX1 and MUC13 and their substantial impact on Wnt/β-catenin signaling in colorectal cancer." (PMID 39309442, 2024). "MUC13 was demonstrated to enhance TNF-induced NF-κB activation, subsequently triggering the pathway and protecting colorectal cancer cells from apoptosis, with its high expression associated with tumor progression and metastasis." (PMID 39309442, 2024). "Previous studies demonstrated MUC13 expression on the apical surface of polarized epithelial cells, and cytoplasmic and nuclear localization was observed in colorectal cancer and during metastasis." (PMID 38345099, 2024). "This interaction correlates with worsened disease outcomes and higher mortality rates, underscoring the potential of the RUNX1/MUC13 pathway as a target for therapeutic intervention in colorectal cancer." (PMID 39309442, 2024). "Given our in vitro findings, MUC13 knockdown counteracted the proliferative, migratory, and invasive effects induced by RUNX1 on colorectal cancer cells, prompting a deeper exploration of MUC13's role in RUNX1-driven in vivo tumor progression and metastasis." (PMID 39309442, 2024). "Collectively, these findings indicated that MUC13 expression levels modulated the metastatic function of RUNX1 in vivo, suggesting that RUNX1 facilitated colorectal cancer cell metastasis partially via MUC13." (PMID 39309442, 2024). "We next investigated MUC13 expression in colorectal cancer cell lines and found increased mRNA and protein levels compared to normal cells." (PMID 39309442, 2024). "All these findings were consistent with the conclusion that MUC13, regulated by RUNX1 transcription in colorectal cancer tissues, was associated with aggressive clinical features and poor prognosis." (PMID 39309442, 2024). "The results demonstrated the pivotal role of the interaction between the transcription factor RUNX1 and MUC13 in modulating colorectal cancer malignancy via the Wnt pathway." (PMID 39309442, 2024). "MUC13 overexpression has previously been described in GC and such aberrant MUC13 signaling is known to protect colorectal cancer cells from death via NF-kB pathway activation thereby impacting on therapeutic efficacy and disease outcome." (PMID 37085819, 2023). "MUC13 has been found to be highly expressed by human colorectal carcinomas as demonstrated by immunochemistry in 99 colorectal cancer cases." (PMID 35692787, 2022). "Based on these findings, it was hypothesized that RUNX1 and MUC13 could influence the malignant phenotype of colorectal cancer by modulating the activity of the Wnt pathway." (PMID 39309442, 2024). "Particularly noteworthy is the research on MUC13 in colorectal cancer." (PMID 39309442, 2024). "From these observations, we inferred that RUNX1 and MUC13 might influence the malignancy of colorectal cancer via the Wnt pathway activity." (PMID 39309442, 2024).
colorectal cancer (continued). "Furthermore, RUNX1 enhanced the progression and metastatic capabilities of colorectal cancer by upregulating MUC13, which resulted in an increased EMT phenotype and amplified Wnt/β-catenin pathway activity." (PMID 39309442, 2024). "MUC13 can promote nuclear factor-κB (NF-κB) activation to prolong colorectal cancer cell survival." (PMID 27911274, 2017). "Silencing MUC13 can improve the sensitivity of colorectal cancer cells to chemotherapy." (PMID 27911274, 2017). "Our data identify MUC13 as a central regulator of TJ strength and paracellular passage, which has important implications for the role of this TM mucin in IBD and colorectal cancer development." (PMID 38345099, 2024). "Considering the critical role of EMT in tumor progression, invasion, and metastasis 35, this study investigated the regulatory function of RUNX1 in modulating MUC13 and its subsequent influence on the EMT phenotype in colorectal cancer cells." (PMID 39309442, 2024). "MUC13 is upregulated during IBD and colorectal cancer, correlating with increased pro-inflammatory responses, cell growth and migration." (PMID 38345099, 2024). "Moreover, a significant positive correlation between the expressions of MUC13 and RUNX1 in colorectal cancer tissues provided new insights into RUNX1's role in promoting malignant behavior in colorectal cancer." (PMID 39309442, 2024). "Subsequent validation, employing various online databases and tissue microarrays, demonstrated a significant elevation in MUC13 expression in colorectal cancer tissues compared to adjacent non-tumorous tissues." (PMID 39309442, 2024). "However, the mechanisms driving colorectal cancer metastasis through MUC13 have not been well elucidated, and the interplay between MUC13 and RUNX1, both critical in CRC and liver metastasis, has not been established." (PMID 39309442, 2024).
colon cancer (6 papers, 2018 to 2024). "It has been shown that MUC13 is cytoplasmic and overexpressed in metastatic colon cancer cells but apically located in normal adjacent control cells." (PMID 30700707, 2019). "We determined the expression and localization of MUC13 in HRT18 colon cancer cells." (PMID 38345099, 2024). "Single-cell migration is enhanced in colon cancer cells with MUC13 overexpression." (PMID 38345099, 2024). "MUC13 protein expression has been implicated as a marker of several diseases, including numerous cancers, such as gastric, ovarian and colon cancer, inflammation and Helicobacter infection, suggesting that MUC13 may be a general signal of cellular infection." (PMID 30700707, 2019). "For instance, colon cancer biomarkers CEACAM1 and MUC13 could be found in MVs derived from colon cancer cells, which could assist in the diagnoses of colorectal cancers." (PMID 36045692, 2022).
hepatocellular carcinoma (5 papers, 2019 to 2025). A malignant tumor that arises from hepatocytes. "A recent study has also suggested that MUC13 expression promotes cellular growth in hepatocellular carcinoma via influencing Wnt signaling and its interaction with beta-catenin." (PMID 37793774, 2023). "Using genome-wide dual RNA sequencing of flow-sorted infected and uninfected hepatoma cells we show that the human mucosal immunity gene, mucin-13 (MUC13), is strongly upregulated during Plasmodium exoerythrocytic hepatic-stage infection." (PMID 30700707, 2019). "Examples include targeting EGFR and c-Met in NSCLC or GPC3 and MUC13 in hepatocellular carcinoma." (PMID 41348261, 2025). "Additionally, it has been demonstrated that the overexpression of MUC13 significantly correlates with poor prognosis in hepatocellular carcinoma, attributed to its role in activating Wnt signaling." (PMID 39309442, 2024). "Similarly, MUC13 has been demonstrated to activate the Wnt signaling pathway in hepatocellular carcinoma, promoting tumor progression through β-catenin activation 25,31." (PMID 39309442, 2024). "We confirm MUC13 transcript increases in hepatoma cell lines and primary hepatocytes." (PMID 30700707, 2019). "Particularly noteworthy is that previous research has shown that MUC13, through its interaction with GCNT3, activates the GSK3β/β-catenin signaling pathway, promoting hepatocellular carcinoma progression 31, a key focus of this study." (PMID 39309442, 2024).
COVID-19 (3 papers, 2021 to 2023). A disease caused by infection with severe acute respiratory syndrome coronavirus 2. "It is interesting to note that MUC21 mRNA expression was only selected as a variable associated with COVID-19 severity, whereas MUC13, MUC4, and MUC6 mRNA expression were uniquely identified as variables indicative for COVID-19 presentation." (PMID 34448730, 2021). "A significant increase in MUC13 mRNA expression was seen in the COVID-19 patient groups compared with healthy controls and the mild non–COVID-19 group, whereas MUC21 mRNA expression was only significantly increased in the mild COVID-19 patient group." (PMID 34448730, 2021). "By using the same approach, we also showed that age and mRNA expression of MUC1, MUC2, MUC4, MUC6, MUC13, MUC16, and MUC20 were the most accurate variables associated with the presence of COVID-19 among symptomatic patients (AUCROC = 91.8%; sensitivity: 90.6%; specificity: 93.3%)." (PMID 34448730, 2021).
esophageal cancer (3 papers, 2020 to 2024). A primary or metastatic malignant neoplasm involving the esophagus. "Therefore, it may provide extremely important clues for finding new targets for the treatment of esophageal cancer by studying the underlying mechanism of MUC13 in the development of esophageal cancer." (PMID 37395858, 2023). "The qRT-PCR assay and western blot experiments were taken to study the mechanism of MUC13 regulating the proproliferation and antiapoptotic of esophageal cancer." (PMID 37395858, 2023). "In brief, silencing of MUC13 was effectively achieved by infection of lentiviral-mediated siRNA in esophageal cancer cells." (PMID 37395858, 2023). "The results showed that MUC13 was overexpressed in esophageal cancer tissues and cell lines (EC9706 and ECA109 and TE-1), especially in EC9706 and ECA109 cells, but low expressed in human esophageal epithelial cell line (HEEC)." (PMID 37395858, 2023). "In this study, it was found that the MUC family protein MUC13 gene is the fourth gene based on differential expression level in the public cancer database (Oncomine), but there are few reports on the research of MUC13 in esophageal cancer." (PMID 37395858, 2023). "In this study, we researched the biological and clinical significance of MUC13 in esophageal cancer and its carcinogenic molecular mechanisms, providing a new perspective for esophageal cancer treatment." (PMID 37395858, 2023). "This study proved that MUC13 is an important molecule that regulates the O-glycan process and then affects the progress of esophageal cancer." (PMID 37395858, 2023). "Next, silencing MUC13 inhibits proliferation, blocks cell cycle progression, and promotes cell apoptosis in vitro, and restrains the growth of esophageal cancer tissues in vivo." (PMID 37395858, 2023). "In this study, we confirmed that GLANT14, MUC3A, MUC1, MUC12, and MUC4 regulatory factors which related to the O-glycan process were overexpressed and downregulated with MUC13 knockdown in esophageal cancer cells, resulting in insufficient tumor growth and proliferation." (PMID 37395858, 2023). "This may be due to the high expression of MUC13, being related to specific types of esophageal cancer, and requires to be further identified." (PMID 37395858, 2023). "Therefore, the results proved that MUC13 knockdown restrains the tumorigenicity of esophageal cancer." (PMID 37395858, 2023). "In this study, we found that the MUC family protein MUC13 gene is the fourth gene based on differential expression level in the public cancer database (Oncomine), but there are few reports on the research of MUC13 in esophageal cancer." (PMID 37395858, 2023). "Therefore we guess that MUC13 can affect the development of esophageal cancer by regulating the O-glycan process, and it is hoped to become a potential therapeutic target of esophageal cancer with certain clinical value." (PMID 37395858, 2023). "However, the relevance between the utterance level of MUC13 and the clinical classification of patients with esophageal cancer needs further study." (PMID 37395858, 2023). "In all, this study lays a foundation for elucidating that MUC13 affects the proliferation and apoptosis of esophageal cancer and indicates MUC13 may be used as a latent therapeutic target for esophageal cancer and has certain clinical value." (PMID 37395858, 2023). "In addition, the expression of MUC13 mRNA level in human esophageal cancer cell lines (EC9706 and ECA109 and TE-1) was measured by qRT-PCR." (PMID 37395858, 2023). "In all, these findings indicate that MUC13 has overly expression in esophageal cancer." (PMID 37395858, 2023). "MUC13 may be a novel therapeutic target for patients with esophageal cancer." (PMID 37395858, 2023). "Therefore, it proves that MUC13 as an important molecule regulating the O-glycan process, and could affect the process and development of esophageal cancer in this study." (PMID 37395858, 2023).
esophageal cancer (continued). "Therefore, the invasion and metastasis of MUC13 in esophageal cancer remain to be further studied." (PMID 37395858, 2023). "Therefore, it is speculated that the characteristics of MUC13 related to cancer can be used for the diagnosis and prognosis prediction of esophageal cancer." (PMID 37395858, 2023). "However, the role and regulatory mechanism of MUC13 in the progression of esophageal cancer remain unclear." (PMID 37395858, 2023). "In summary, these data indicate correlation between the proproliferation and antiapoptotic effects of MUC13 with the expression of GLANT14, MUC3A, MUC1, MUC12 and MUC4 in esophageal cancer." (PMID 37395858, 2023). "In previous studies, it was found that MUC13 is abnormally expressed in a variety of malignant tumors, but its function and mechanism in the invasiveness and malignant progression of esophageal cancer have not been studied in depth." (PMID 37395858, 2023). "In this study, we found that MUC13 is highly expressed in some human esophageal cancer tissues compared with adjacent nontumor tissues." (PMID 37395858, 2023). "At present, although there are evidences that MUC13 can be used as biomarkers of esophageal cancer, their functions and mechanisms in depth have not been studied yet." (PMID 37395858, 2023). "Although our study investigated the effect and the potential mechanism of MUC13 on the proliferation and apoptosis of them, the role of MUC13 on the migration and invasion of esophageal cancer cells has not been further studied." (PMID 37395858, 2023). "There appears a significant difference in MUC13 positive cell percentage between esophageal cancer tissues and adjacent nontumor specimens (n = 30, P = 0.01)." (PMID 37395858, 2023). "The expression level of MUC13 was detected in 15 esophageal cancer tissues and 15 pairs of adjacent nontumor tissues by immunohistochemistry (IHC)." (PMID 37395858, 2023). "The expression level of MUC13 in esophageal cancer tissues and adjacent nontumor specimens was measured by IHC." (PMID 37395858, 2023). "Although many studies have demonstrated that MUC13 is abnormally presented in a variety of malignant tumors, its function and mechanism in the invasiveness and malignant progression of esophageal cancer have not been studied in depth." (PMID 37395858, 2023). "However, the potential function, prognosis, and therapeutic significance of MUC13 in esophageal cancer have not been determined." (PMID 37395858, 2023).
lung carcinoma (3 papers, 2024 to 2025). "Subsequent mechanistic insights have elucidated that MUC13 facilitates lung cancer advancement by stimulating the ERK/JNK/p38 signaling cascade." (PMID 40655139, 2025). "Investigations leveraging transplanted tumor models have conclusively shown that silencing MUC13 delays the progression of lung cancer xenografts and curbs the expression of Ki-67, a pivotal proliferation marker." (PMID 40655139, 2025). "Evidence suggests that MUC13 acts as an oncogenic glycoprotein and regulates the progression of esophageal and lung cancer." (PMID 39682235, 2024).
renal cell carcinoma (3 papers, 2017 to 2023). "Mucin13 (MUC13) is a transmembrane glycoprotein that is aberrantly expressed in ovarian and gastro-intestinal tumors, but its role in renal cell carcinoma remains elusive." (PMID 27911274, 2017).
cholangiocarcinoma (2 papers, 2022 to 2024). A carcinoma that arises from the intrahepatic biliary tree (intrahepatic cholangiocarcinoma) or from the junction, or adjacent to the junction, of the right and left hepatic ducts (hilar cholangiocarcinoma). "Interestingly, MUC13 expression has been associated with several types of cancers including cholangiocarcinoma, pancreatic, hepatocellular and colorectal." (PMID 36497057, 2022).
colorectal tumor (2 papers, 2022 to 2024). "Additionally, two independent GEO microarray datasets (GSE14297 and GSE37182) were employed to assess the differential expression of MUC13 between normal and colorectal tumor tissues." (PMID 39309442, 2024).
gastric adenocarcinoma (2 papers, 2020 to 2023). "Gastric adenocarcinomas with an intestinal mucin environment or high-level MUC13 expression are associated with poor survival." (PMID 37085819, 2023).
gastric tumor (2 papers, 2022 to 2023). "Interestingly, Lactobacillus, Neisseria, Prevotella, and Veillonella were enriched in gastric tumor samples with high MUC13 expression." (PMID 37085819, 2023). "Whether the upregulation of MUC13 has similar capacities to inhibit gastric tumor cell death requires further investigation." (PMID 37085819, 2023).
inflammatory bowel disease (2 papers, 2020 to 2023). A spectrum of small and large bowel inflammatory diseases of unknown etiology. "MUC13 has been reported to be highly expressed on the human intestinal mucosal surface, and polymorphism in MUC13 is related to inflammatory bowel disease." (PMID 31624342, 2020). "Overexpression of the transmembrane mucin MUC13, as seen in inflammatory bowel diseases (IBD), could potentially impact barrier function." (PMID 37174625, 2023).